GZMB (granzyme B)
Diseases named in the same sentence as GZMB in open-access papers (continued):
Sharing a sentence is not in itself a finding about the gene and the disease.
tumor (continued). "This combination treatment exhibits marked anti-tumor efficacy with decreased Tregs and MDSCs and increased IFN-γ+ and granzyme B+ CD8+ T cells." (PMID 37700339, 2023). "Since the effector activity of T cells is also affected by the intratumoral environment, the levels of IL-2, IFN-γ and granzyme B (GZB) were measured by flow cytometry in spleen and tumor tissues on 21 and 28 daft." (PMID 37736849, 2023). "PD-L1 antibody and SR59230A treatment increased the production of granzyme B and perforin by PD1+CD8+ cells in the tumour mass, thereby stimulating immune activation in NB TME." (PMID 37887559, 2023). "Immunohistochemically, tumor cells from all cases were positive for CD3ε and EBER, and 98.8% of cases were positive for the cytotoxic marker T‐cell intracellular antigen‐1/granzyme B. Positive CD56 immunostaining was observed in 72.8% (59/81) of cases." (PMID 36114786, 2023). "Results confirmed an increased production of granzyme B and perforin by PD-1+CD8+ cells in tumor mass of SR59230A-, αPD-L1- or SR59203A + αPD-L1-treated mice compared to vehicle." (PMID 36854895, 2023). "In immune‐intact mice CDXs, apart from inhibiting tumor growth, ANO1 knockdown also increased the anti‐tumor immune activity, marked by increased infiltration/expression of CD8+ T cells/IFN‐γ/TNF‐α/granzyme B/IL‐13 and reduced PD‐L1 expression." (PMID 37341301, 2023). "Granzyme B is a serine protease released by CD8+ T cells and natural killer cells and functions as a downstream effector of tumor cytotoxic T cells." (PMID 37607911, 2023). "Consistently, the tumor-infiltrating GZMAhigh NK subcluster expressing a high level of cytotoxic genes (GZMA, GZMB, GZMK, GZMM, GZMH, PRF1, and GNLY) and FASL and TRAIL genes was most enriched in the PD-1+SMI group." (PMID 37430270, 2023). "Immunohistochemical staining for GZMB, the key CD8 + T-cell effector molecule, revealed that IAC tumors had lower GZMB level, indicating the attenuated activity of CD8 + T cells in IAC tumours." (PMID 37303063, 2023). "In line with the scRNA-Seq data, IF staining results revealed that MIB2 knockdown increased the tumor-infiltrated CD8+ T cell population and granzyme B release in B16-F10 tumors from C57BL/6 syngeneic mice." (PMID 36719382, 2023). "Next, we quantified the proliferating bona fide cytotoxic CD3 (GZMB+), FOXP3+, CD11c+ immune cells, and tumor cells (Pan-CK+) in the stroma and tumor areas by staining for the proliferation marker Ki67." (PMID 37349318, 2023). "The expressions of cytokines, IFNγ, granzyme B (GZMB), and IL-2 in the sorted T cells are attenuated in the CAP-treated mice, indicating that the functions and activities of tumor-infiltrating T cells are impaired by CAP treatment." (PMID 37189453, 2023). "In this study, the perforin, granzyme B, and granzyme A secreted by CTL cells in tumor tissue were evaluated by immunohistochemical staining." (PMID 37529049, 2023). "The activity of tumor-infiltrating cytotoxic CD8+ T cells, as measured by granzyme B levels, was reduced after alisertib treatment, but the addition of anti–PD-L1 antibody restored this activity." (PMID 36928177, 2023). "For example, in human, CD103+ TRM cells can produce granzyme B (GZMB) and IFN-γ, which can enhance recruitment of monocytes, NK cells, and XCR1+ cDC1 to the tumor site, resulting in anti-tumor." (PMID 38130725, 2023). "Accordingly, FGFBP2+NKT cells expressed the highest levels of cytotoxic genes, such as GZMB, GZMH, PRF1, and GNLY, indicating that FGFBP2+NKT cells had the strongest tumor-killing effects." (PMID 38065972, 2023). "in bladder cancer highlighted the presence of distinct subsets of CD4+ T CTL in the tumor microenvironment, expressing different combinations of cytolytic genes (GZMA, GZMB, GZMK, PRF1)." (PMID 37965314, 2023). "All NaMiX significantly enhanced the cytolytic activity of NK and CD8+ T cells against Raji tumour cells and HIV-1+ ACH-2 cells by increasing degranulation, release of granzyme B, perforin and IFN-γ." (PMID 37936122, 2023).
tumor (continued). "We further analyzed the tumor supernatants of both tumor types treated with MK2 KO CD8+ T cells compared to control and treated with WT CD8+ T cells and found soluble FAS and GZMB to be increased." (PMID 37415974, 2023). "Analysis of intratumoral lymphocytes in sgSlc38a2-transduced MC38 tumours revealed a higher frequency and number of intratumoral CD8+ T cells, including those expressing IFNγ, TNF or granzyme B, indicative of enhanced effector phenotypes." (PMID 37407815, 2023). "Intriguingly, our investigation into gene expression at the protein level has unveiled increased production of granzyme B, IFN-gamma, TNF-alpha, and soluble Fas ligand (sFasL) pin-transduced TCR-like CAR-T cells upon encountering SK-Mel-37 tumor cells." (PMID 37894816, 2023). "Soluble GZMB and FAS were also found in tumor supernatants, but at lower levels compared to tumors obtained from mice treated with Th2 cells." (PMID 36376448, 2023). "One of the main methods by which NK cells destroy tumor cells is by producing cytotoxic granules containing perforin (PRF1) and GzmB." (PMID 36816977, 2023). "CD8+ T cells combines with T-cell receptors and tumor cells to generate IFNg, TNF, and granzyme B and eliminate tumor cells." (PMID 36505472, 2022). "Along with tumor cells, Tregs produce IL-10 and TGF-β that have inhibitory effects on CD8+Granzyme B+ cytotoxic T cells and CD57+Granzyme B+ NK cells." (PMID 35327381, 2022). "Histogram analysis of pixel intensity in images of tumors stained for granzyme B showed that PTX, IMT, and IMT/PTX had significantly different patterns of intensity compared to control tumor images on day six (p < 0.0001 for all comparisons)." (PMID 35214172, 2022). "Tumor-bearing mice treated with combination therapy showed higher amounts of CD8+ TILs that expressed IFN-γ, Granzyme B, Perforin, TNF-α, TRAIL and FasL than untreated mice, OX or TIGIT mAb alone." (PMID 36389751, 2022). "The tumor-infiltrating CD8 T cells kill the tumor cells by releasing apoptosis-inducing cytotoxic proteins (e.g. interferon gamma, IFN- γ) or granules (e.g. perforin and granzyme B)." (PMID 35756611, 2022). "We assessed tumor-infiltrating CD8+ T cells for expression of the effector lytic molecule, granzyme B, as well as the inhibitory PD-1 receptor." (PMID 36123697, 2022). "The latest reports in the literature suggest the anti-tumor activity of β-endorphins due to the activation of interferon gamma (IFN-gamma), granzyme-B, and perforin mediated by NK cells and macrophages." (PMID 36078233, 2022). "The immune cytotoxic/effector genes were mainly expressed by T and NK cells, some of which were commonly up‐regulated in the inflammation and tumor regions in the Stereo‐seq slides, including GNLY, GZMA, GZMB, and NKG7." (PMID 35986392, 2022). "The suppressive effects of tumor-treated Cd36−/− BMDMs on CD8+ T cells were reduced when compared with WT BMDMs, as demonstrated by increased GzmB and IFNγ expression of CD8+ T cells." (PMID 36184646, 2022). "We have previously characterised a PET imaging-based peptide biomarker targeting granzyme B ([18F]AlF-mNOTA-GZP) and demonstrated that it can successfully stratify tumours responding to combinations of immune therapeutics from non-responding tumours." (PMID 35057046, 2022). "The tested candidates induced release of IL-2, granzyme B, perforin, and IFNγ from human PBMC in response to UACC-257 tumor cells." (PMID 35645207, 2022). "Expression of granzyme B and caspase 3 in treated PTO CK20+ tumor cells decreased when comparing iPTO set MCC2 to later sets MCC7 and MCC9." (PMID 35974123, 2022). "Both the density and proportion of CD4+ Granzyme B+ and CD8+ Granzyme B+ T cells exhibited an increase post-vaccination, indicating the enhancement of the infiltration of T cells into tumor tissues." (PMID 36248865, 2022).
tumor (continued). "The combination therapy increased CD8+:CD4+ ratios and led to an increase in serine protease granzyme B, Ki67, and killer cell lectin like receptor G1 (KLRG1) in tumor infiltrating CD8+ cells." (PMID 36203599, 2022). "In GBM, specifically, tumor-derived PGF induces the generation of TGFβ+ regulatory B cells, which suppress CD8+ T-cell proliferation and release of perforin and granzyme B." (PMID 36046049, 2022). "We also performed IHC staining on both Pan02 subcutaneous and KPC orthotopic tumour tissues to examine the expression level of various markers of immune activation, including CD8, granzyme B, CD62L, CD49b and CD86." (PMID 35174623, 2022). "TGF-β enhanced the migration and anti-tumor function of Vδ2 T cells through upregulating the expressions of CD54, CD103, IFN-γ, IL-9 and granzyme B." (PMID 35747139, 2022). "CD8+ T cells in the lung of 4TO7-Lin28B tumor-bearing host included a smaller CD44+CD62L− T cell population and expressed lower CTLA-4 and granzyme B." (PMID 35173168, 2022). "GzmB expression was also detected in higher percentages of CD4 and CD8 tumor infiltrating lymphocytes (TILs) in vaccinated mice." (PMID 36569934, 2022). "On the other hand, the levels of IFN-γ, perforin and granzyme B in CD8+ T cells were significantly increased after cryo-thermal therapy, which indicated that CD8+ T cells killed tumor cells via a perforin-dependent pathway." (PMID 35874660, 2022). "CD8-05-FGFBP2 cluster exhibited a CD8+ effector phenotype, upregulating genes involved in cytotoxicity and anti-tumor activity: FGFBP2, GNLY, FCGR3A, GZMH, PRF1, TGFBR3, and GZMB." (PMID 36350695, 2022). "We sought to compare the prognostic value of CD8 with downstream indicators of active immune cell function, specifically granzyme B (GZMB) and CD68 in the tumour microenvironment." (PMID 36114487, 2022). "Tumor-infiltrating CD8+ T cells from aPD-1 single-treated mice showed an increase of IFNγ, TNFα, and Granzyme B expression compared to untreated controls." (PMID 34423375, 2022). "CD103+ CD4+ T cells exhibit an immunosuppressive phenotype and high retention capacity in GC tumor tissues, leading to CD8 + T cell dysfunction, and granzyme B (GZMB), interferon-γ (IFN-γ), tumor necrosis factor α (TNF-α), and perforin (PRF-1) reduction." (PMID 36341377, 2022). "Overall, CpG/aOX40 treatment sustained high CD8+ T-cell:Treg ratio and granzyme B production, suggesting that this treatment can increase CD8+ T-cell functionality and the ability to initiate tumor killing." (PMID 35760778, 2022). "In the study, we found that, in comparison to wild-type animals, Tmem176b knockout lowered the expression of IFN-γ, PRF1 and GZMB in TIL CD8+ T cells, indicating that the function of tumor-infiltrating T cells was suppressed." (PMID 35399535, 2022). "This was associated with an increased cytotoxic immune response in the tumor microenvironment characterized by increased CD8+ T cells and enhanced Granzyme B production during BRB extract-mediated HNSCC chemoprevention." (PMID 36016924, 2022). "GZMB and PFN can also be repressed by miR-27, and knockdown of miR-27 increases in vitro cytotoxicity, leading to decreased tumor growth in a human tumor xenograft model." (PMID 36248881, 2022). "Furthermore, activation of autophagy in tumor cells has been shown to protect against lytic granule attack through multiple mechanisms in vitro and in vivo, including the direct autophagic degradation of NK -derived granzyme B in the lysosomal compartment, ultimately impairing target cell lysis." (PMID 35592329, 2022). "However, tumor cells often downregulate HLA-I and allow effector NK cells to be activated by immunoreceptor tyrosine-based activation motifs (ITAMs) in intracellular domains, resulting in the release of cytokines, perforins and granzyme B and leading to tumor cell death." (PMID 35342342, 2022).
tumor (continued). "Tumour infiltration of CD8+ T cells was also enhanced by napabucasin treatment, and exhibited lower levels of LAG‐3, PD‐1 and high levels of Granzyme B, Perforin, IFNγ in the napabucasin‐treated mice than in the control group." (PMID 35665592, 2022). "As another role of PRF1 in anti-tumor immune response, PRF1 also maintains the expression of granzyme B in cytotoxic cells." (PMID 35163049, 2022). "With correlating gene expression profiles of cytotoxic T lymphocyte (CTL) markers (CD8A, CD8B, GZMA, GZMB, and PRF1) with T-cell characteristics, the TIDE algorithm predicts immunotherapy of tumor patients." (PMID 36618968, 2022). "Together with granzyme B and perforin, IFN-γ acts as a cytotoxic cytokine that initiates apoptosis in tumor cells." (PMID 36389735, 2022). "Three genes (ELANE, NLRP7, and CASP5) were downregulated, whereas seven others (GSDMC, IL1A, NOD2, GZMB, GSDMA, IL1B, and PLCG1) were overrepresented in the tumour group." (PMID 35087586, 2022). "NK cells regulate cellular cytotoxic activity and cytokine production through cytotoxic proteins (e.g. perforin, granzyme B, FasL, and TRAIL), which are important participants in the controlling tumor progression." (PMID 36068970, 2022). "We observed a high positive correlation between 68Ga-grazytracer tumor uptake values determined via in vivo PET imaging and granzyme B levels quantified by ex vivo Western blotting (Pearson’s r = 0.7168, P < 0.01) and ELISA (Pearson’s r = 0.7337, P < 0.01)." (PMID 35788116, 2022). "Bulk RNA-seq analysis of sorted tumour-infiltrating CD8+ T cells revealed higher expression of IFNG, GZMB and PRF1 in post-treatment samples, indicating enhanced cytotoxic potential of tumour-infiltrating CD8+ T cells following PI3Kδi treatment." (PMID 35508656, 2022). "Following the combination therapy in the tumor mouse model, the results showed that the number of PD-1+ CD8+, CD8+ granzyme B+, and CD8+ IFN-γ+ T cells significantly increased, and finally, the size and weight of the tumor mass markedly reduced." (PMID 36010836, 2022). "It has been reported that GZMB and PRF1 are highly expressed in tumour tissues, and it was found that tumour tissues with high expression of GZMB and PRF1 have higher infiltration of CD8+ T cells and better tumour prognosis." (PMID 35473583, 2022). "Meanwhile, IFNα released by IFNα-MSCs enhances the expression of GZMB in CD8+ T cells and thus promotes their ability to eradicate tumor cells." (PMID 35145233, 2022). "Ag-specific CD8 T cells newly recruited into the tumor expressed minimal levels of PD-1, LAG-3, and CD39 alongside reduced amounts of Granzyme B compared with the retained populations." (PMID 35472220, 2022). "CD8+ T cells, as the prime anti-tumor cells, can destroy cancerous cells by secreting perforin and granzyme B through the Fas/FasL pathway once they contact tumor cells or release IFN-γ and TNFα to eliminate tumor cells." (PMID 35069907, 2022). "While both CAR-NKs products showed selective and effective tumoricidal activity towards cell lines and tumor samples of T-ALL, the bivalent model scored superior antitumor effects and generated higher levels of granzyme B and IFN-γ." (PMID 36552738, 2022). "The results demonstrate that the enhanced anti-tumor immune response in combination-treated group was accompanied by a pronounced upregulation in the expression of IFN-γ (~3.9-fold) and cytotoxic granzyme B (~2.3-fold) at the level of total tumor tissue." (PMID 36605208, 2022). "The distribution of immune cell density showed a wider interquartile range (IQR) for all tumour regions (CT, FR, ME) than in the normal colorectal epithelium for all assessed antigens (CD8, GZMB, CD68, CD163)." (PMID 36114487, 2022). "Combined high expression of GZMB and CD68 within 25 μm to tumour cells is an independent prognostic factor in CRC and of superior prognostic value to the well-established CD8 in TNM stage II cancers." (PMID 36114487, 2022).
tumor (continued). "Consistently, in those B16F10 tumor-bearing Jα18-/- chimeric mice, α-GC induced less IFN-γ and IL-4 production in intratumoral CD45.2+Vdac1+/- iNKT cells, despite their normal granzyme B production." (PMID 36741382, 2022). "CD8+, GZMB+, CD68+ and CD163+ cells showed significant correlation throughout the majority of assessed tumour regions (centre, front and microenvironment)." (PMID 36114487, 2022). "This robust anti-tumor effect correlated with the increase in intratumoral CD40+ DCs and the frequency of granzyme B+/IFN-γ+/TNF-α+ polyfunctional OVA peptide-specific CD8+ T cells." (PMID 36311701, 2022). "In tumour xenograft tissues, α5-nAChR expression was related to PD-L1, Jab1, pSTAT3, CD4 and granzyme B expression (GB)." (PMID 35971127, 2022). "We found that RCE plus oxaliplatin apparently activates hPD-1 tumor-infiltrating CD8+ T cells, resulting in elevations of released interleukin-2 (IL-2) and granzyme B (GrB), and kills hPD-L1 MC38 CRC cells." (PMID 36139451, 2022). "Through the secretion of the cytolytic molecules such as Granzyme B and TRAIL, pDCs have been shown to display direct cytotoxic properties against tumor cells." (PMID 36232698, 2022). "In 2020, it was reported that granzyme B (GzmB) can activate pyroptosis by cleaving GSDME, which stimulates antitumor immune responses and further inhibits tumor growth." (PMID 36523974, 2022). "In particular, six tumor cytotoxicity-related molecules (GZMA, GZMB, GZMH, IFNG, FASLG, and NKG7) from T cells had significantly higher levels in the BM than in PB." (PMID 40977909, 2022). "RvD high tumors proved increased gene expression levels of anti-tumor effectors, including GZMA, GZMB, PRF1, and cytolytic score, suggesting higher cytotoxic activity in the tumor microenvironment." (PMID 35742918, 2022). "Granzyme B (GZMB), as an inflammatory gene and cytotoxic gene, participated in immune response and tumor cell killing." (PMID 35432539, 2022). "Of all T-cell subsets, CTLs are the primary tumoricidal actors, mediating tumor killing via perforin (PFN) and granzyme B (GZMB)." (PMID 36248881, 2022). "By secreting cytolytic factors and cytokines such as granzyme B and perforin, DBMN-T successfully eliminated tumor cells." (PMID 35672752, 2022). "Interestingly, our ex-vivo studies showed that S100A8 is a potent activator of NK cells, as indicated by increased expression of granzyme B, thus it is plausible that treating tumor-bearing mice with S100A8 may induce activation and function of NK cells without altering their numbers." (PMID 35655772, 2022). "When we stimulated these cytokine-induced CD3+CD56+ NK-T-like cells with K562 tumor cells, we found that the IFN-γ release, granzyme B level, and proliferation ability were significantly increased." (PMID 35783158, 2022). "Cytotoxic T cells are activated by recognizing tumor antigen presented by MHC class I molecule, bind to tumor cells and secrete granzyme B and perforin, and eventually induce tumor cell apoptosis." (PMID 36293435, 2022). "The newly differentiated tumor-specific effector T cells proliferate and migrate to the TME where they release granzyme B and perforin to promote tumor cell death." (PMID 35890355, 2022). "Results from this study show that noninvasive granzyme B-based PET imaging with [68Ga]-NOTA-GZP is a novel and valuable approach for measuring effector cell activation and predicting tumor response to combination chemotherapy and IMT in TNBC." (PMID 35214172, 2022). "In a murine melanoma model, intratumoral administration of this NP formulation resulted in higher frequencies of tumor-infiltrating T cells, elevated frequencies of IFN-γ and granzyme B expressing CD3+ T cells, and virtually abrogated tumor growth." (PMID 35693776, 2022).